TRAM1L1 (translocation associated membrane protein 1 like 1)
Description:
Stimulatory or required for the translocation of secretory proteins across the ER membrane.
Synonyms: MGC26568
Tractability: Antibody: UniProt predicts a signal peptide or a membrane-spanning region.
Gene: Protein-coding gene on chromosome 4 (117,083,554 to 117,085,576, reverse strand). Ensembl gene ENSG00000174599.
Subcellular location: Endoplasmic reticulum membrane
Subcellular location (Human Protein Atlas): Mitochondria
Gene Ontology:
Molecular function: protein binding
Biological process: protein insertion into ER membrane; SRP-dependent cotranslational protein targeting to membrane, translocation
Cellular component: endoplasmic reticulum membrane; membrane
Genetic constraint (gnomAD): Loss-of-function variants: 0 observed, 1.28 expected, observed/expected ratio (o/e) 0, 90% interval 0 to 1.63. That is too few expected variants to judge how well the gene tolerates losing a copy. Missense variants: 451 observed, 465.82 expected, observed/expected ratio (o/e) 0.97, 90% interval 0.9 to 1.05. Synonymous variants: 189 observed, 175.82 expected, observed/expected ratio (o/e) 1.07, 90% interval 0.95 to 1.21.
Homologues: Orthologues: macaque TRAM1L1 (96% identical), rabbit TRAM1L1 (86% identical), dog TRAM1L1 (79% identical), pig TRAM1L1 (76% identical), rat Tram1l1 (75% identical), mouse Tram1l1 (75% identical), tropical clawed frog tram1 (64% identical), zebrafish tram1 (57% identical), Drosophila melanogaster TRAM (37% identical), Caenorhabditis elegans tram-1 (31% identical). Paralogues in human: TRAM1 (72% identical), TRAM2 (45% identical).
Diseases named in the same sentence as TRAM1L1 in open-access papers:
TRAM1L1 is named in the same sentence as 12 diseases in open-access papers, as found by Europe PMC text mining. Sharing a sentence is not in itself a finding about the gene and the disease. The quoted sentences say what the papers report.
embryonal carcinoma (2 papers, 2022 to 2025). A non-seminomatous malignant germ cell tumor characterized by the presence of large germ cells with abundant cytoplasm resembling epithelial cells, geographic necrosis, high mitotic activity, and pseudoglandular and pseudopapillary structures formation. "A recent analysis of the Cancer Genome Atlas demonstrated that KIT, KRAS, and NRAS gene variants were observed only in seminoma, while gene variants in B3GNT8, CAPN7, FAT4, GRK1, TACC2, and TRAM1L1 occurred only in embryonal carcinoma." (PMID 41426877, 2025). "Mutations in ADAMTS20, ARHGAP10, OR1L4, PDS5A, and RPLP0 were only found in mixed germ cell tumors, while mutations in B3GNT8, CAPN7, FAT4, GRK1, TACC2 and TRAM1L1 were only observed in embryonal carcinoma, and their mutation frequency was around 2%." (PMID 36713456, 2022). "Differences in somatic mutations between subtypes are also of concern, with our results suggesting that mutations in some genes (B3GNT8, CAPN7, FAT4, GRK1, TACC2, and TRAM1L1) occur only in embryonal carcinoma, while mutations in KIT, KARS, and NRAS are observed only in seminoma." (PMID 36713456, 2022). "As described in our results, mutation that only occurs in embryonal carcinoma (B3GNT8, CAPN7, FAT4, GRK1, TACC2 and TRAM1L1) or seminoma (KIT, KARS and NRAS) may be valuable molecular markers and therapeutic targets that need to be considered clinically." (PMID 36713456, 2022).
alcohol abuse (1 paper, 2017). The use of alcoholic beverages to excess, either on individual occasions ("binge drinking") or as a regular practice. "We did, in fact, observe that the same SNPs downstream of TRAM1L1 that were associated with R-lateral ventricle volume were also associated with lifetime alcohol abuse or dependence in our data set (p-values = 1.92 × 10−7 to 2.84 × 10−6)." (PMID 29187748, 2017). "We identified several SNPs in high LD with rs34043524, which is downstream of the TRAM1L1 gene that were associated with right lateral ventricular volume (p = 1.73 × 10−7; FDR q = 0.032) and were also associated with lifetime alcohol abuse or dependence (p = 2.49 × 10−7; FDR q = 0.0375)." (PMID 29187748, 2017).
fibromyalgia (1 paper, 2022). A chronic disorder of unknown etiology characterized by pain, stiffness, and tenderness in the muscles of neck, shoulders, back, hips, arms, and legs. "TRAM1L1 seems to be closely related to chronic widespread musculoskeletal pain (CWP), a common disorder affecting about 5–15% of the population, and one of the main symptoms of fibromyalgia, which has been shown to be associated with an altered gut microbiome." (PMID 36290220, 2022).
schizophrenia (1 paper, 2019). A major psychotic disorder characterized by abnormalities in the perception or expression of reality. "Five of these top eight LD-independent loci (MTHFR, PDE4B, DAOA, ARVCF, TRAM1L1/NDST3) were not located within risk loci identified in the largest schizophrenia GWA study produced by the PGC and three loci (MTHFR, DAOA, ARVCF) had never been implicated by a schizophrenia GWA study." (PMID 31455759, 2019).
TRAM1L1 also shares sentences with these, for which no sentence is quoted: cancer (2 papers); seminoma (2); alcohol dependence (1); Autoimmunity (1); dependence (1); mixed germ cell tumor (1); Obesity (1); tumor (1).